REN (renin)
Diseases named in the same sentence as REN in open-access papers (continued):
Sharing a sentence is not in itself a finding about the gene and the disease.
Hyperglycemia (continued). "Diabetic retinopathy (DR) is a leading cause of vision loss and is primarily driven by chronic hyperglycemia, which induces retinal vascular damage through mechanisms involving vascular endothelial growth factor (VEGF) and the renin-angiotensin system (RAS)." (PMID 40510890, 2025). "In a recent review, Jia and Sowers identified undue renin-angiotensin-aldosterone, sympathetic nervous systems activation, oxidative stress, inflammation and mitochondrial dysfunction as factors that link hyperglycemia to increased blood pressure." (PMID 40802820, 2025). "Studies have demonstrated that hyperglycemia in T2D leads to inappropriate activation of the renin–angiotensin–aldosterone system (RAAS), reduces nitric oxide (NO) availability, and promotes the formation of reactive oxygen species (ROS)." (PMID 40283140, 2025). "Traditionally, its pathogenesis has been attributed to hyperglycemia-induced metabolic disturbances, glomerular hyperperfusion and hyperfiltration, activation of the renin–angiotensin–aldosterone system (RAAS), and oxidative stress." (PMID 41282283, 2025). "The TGF-β1 level was found to be influenced by hyperglycemia management or the administration of drugs that inhibit the renin-angiotensin II–aldosterone system." (PMID 40531227, 2025). "This is likely because hyperglycemia can lead to increased renal perfusion, hyperfiltration, overactivation of the renin-angiotensin system (RAS)." (PMID 39926344, 2025). "In T2D, prolonged hyperglycemia leads to oxidative stress, inflammation, and activation of the renin–angiotensin system, which impairs endothelial function and causes pericyte degeneration." (PMID 40283140, 2025). "Multiple factors contribute to the development of progressive myocardial damage and subsequent fibrosis, including hyperglycemia, increased oxidative stress, fatty acid availability, and activation of the renin-angiotensin-aldosterone system." (PMID 38982515, 2024). "With the accumulation of AGEs and persistent hyperglycemia, the renin-angiotensin-aldosterone system (RAAS) is activated." (PMID 39526249, 2024). "Succinate accumulated in the distal nephron-collecting duct, and activation of GPR91 responded to hyperglycemia through the stored (pro)renin and provoked tissue injury in DKD." (PMID 36742307, 2023). "On one hand, hyperglycemia induces oxidative stress by activating the renin-angiotensin-aldosterone system (RAAS), which leads to renal injury." (PMID 36911691, 2023). "These other components include angiotensinogen at the proximal tubules and renin release by the macula densa, as seen with hyperglycemia-induced mitochondrial succinate production acting on the GPR91 receptor." (PMID 37566054, 2023). "Hyperglycemia and hyperinsulinemia both activate the renin–angiotensin system and angiotensin type 2 receptor expression in blood vessels, which results in vessel wall hypertrophy and fibrosis." (PMID 37240626, 2023). "The secretion of renin in the juxtaglomerular apparatus plays an important role in the activation of intrarenal RAS by hyperglycemia." (PMID 36742307, 2023). "Stress hyperglycemia represents an epiphenomenon of pancreatic β-cell dysfunction, adrenergic and renin-angiotensin-aldosterone system (RAAS) overactivity, hyperglucagonemia, and the increase of FFAs." (PMID 35784538, 2022). "Findings from experimental models of hyperglycemia suggest that TGF-β1, IL-1β, renin, and ALPK1 levels in the kidney or blood is associated with ALPK1-induced fibrotic kidney injury." (PMID 36139553, 2022). "Hyperglycemia increased succinate concentration and succinate receptor activation in the kidney, leading to renin release." (PMID 35936218, 2022). "Several factors have been shown to modulate CD (pro)renin and (P)RR synthesis, including Ang II, sodium intake, and hyperglycemia." (PMID 35710133, 2022).
Hyperglycemia (continued). "Currently available clinical approaches to treating DKD remain limited and mainly involve strict control of hyperglycemia, proteinuria and blockade of the renin-angiotensin system." (PMID 34506229, 2021). "In the present study, in rats with STZ-induced hyperglycemia, renin content was augmented in the plasma and prorenin and renin amounts were increased in the renal medullary tissues." (PMID 34226610, 2021). "Hyperglycemia activates local RAS by upregulating intracellular RAS components including renin, ACE, and chymase (an Ang II-generating enzyme) in mesangial cells, AT1R, AT2R, and renin in endothelial cells, and renin and AT1R in podocytes." (PMID 34289001, 2021). "Currently the management of DN consist of using inhibitor for renin-angiotensin-aldosterone system, beside the control of the hyperglycemia, blood pressure and dyslipidemia." (PMID 32121033, 2020). "The mechanism of osteoporosis in db/db mice is complicated, such as hyperglycemia, AGEs, abnormality of renin-angiotensin system, and leptin." (PMID 32080264, 2020). "Hyperglycemia also contributes to increased activity of local renin-angiotensin-aldosterone system (RAAS) in the heart." (PMID 33224989, 2020). "There is consistent data showing that renal TGF‐β expression increases in DKD6, 51 as it is induced by renin angiotensin system activation, metabolic dysregulation and hyperglycaemia." (PMID 30407737, 2019). "There is also evidence of overactivation of the renin-angiotensin-aldosterone system as consequence of the hyperglycemia, impacting the pathogenesis of the microvascular complications in type 1 diabetes, affecting retina, nerves, and kidney." (PMID 31681167, 2019). "One study indicated the possible mechanism in which AIIRBs attenuate renin-angiotensin system activities induced by hyperglycemia or dyslipidemia." (PMID 30355965, 2018). "Sustained hyperglycaemia has been shown to activate the intrarenal renin aldosterone system which is thought to increase Na+ retention at various sites of the kidney such as distal tubule and collecting duct of the nephron." (PMID 30009183, 2018). "Hyperglycemia, enhanced renin-angiotensin system activity, and elevated levels of circulating cytokines are all clinical manifestations associated with the diabetic condition, and each is known to promote NADPH-derived O2− production." (PMID 26989452, 2016). "The etiology of increased GFR in the setting of elevated blood glucose and HbA1c is incompletely understood, but has been attributed to the effect of hyperglycemia on the renin-angiotensin-aldosterone system (RAAS)." (PMID 26363801, 2015). "The finding that intracellular renin and angiotensin II (Ang II) disrupts chemical communication and impairs metabolic cooperation between cardiomyocytes induced by aldosterone, hyperglycemia, and pathological conditions like myocardial ischemia is discussed." (PMID 26042086, 2015). "Oxidative stress is linking most of the molecular events underlining the pathological process in DN, related to hyperglycemia and AGE, the renin-angiotensin system, TGFβ signaling, and chronic inflammation." (PMID 26491232, 2015). "This increase is correlated with angiotensin II, due possibly to overstimulation of the renin-angiotensin system in response to hyperglycemia." (PMID 23671873, 2013). "The pathogenesis of DN is complex and involves the interaction of many hemodynamic and metabolic signaling pathways, such as hyperglycemia, stretch, growth factors, the renin-angiotensin system, and oxidative stress." (PMID 24103534, 2013). "This study is aimed at exploring the relationship between the abnormalities in H2S metabolism, hyperglycemia-induced oxidative stress and the activation of intrarenal renin-angiotensin system (RAS)." (PMID 24058553, 2013).
Hyperglycemia (continued). "These alterations are induced by chronic hyperglycemia, oxidative stress, activation of the renin–angiotensin–aldosterone system (RAAS), and pro-inflammatory and profibrotic pathway upregulation, especially through transforming growth factor-β (TGF-β) and nuclear factor-kappa B (NF-κB)." (PMID 41302309, 2025). "Hyperglycemia triggers podocyte apoptosis through pathways involving ROS, renin-angiotensin system (RAS), mammalian target of rapamycin (mTOR), and transforming growth factor-beta/SMAD (TGF-β/SMAD) signaling pathway, contributing to podocyte loss and albuminuria in DKD." (PMID 39941397, 2025). "Furthermore, 1.25(OH)2D3 can block the increased activity of intercellular renin, extracellularly released Ang II levels under hyperglycemia conditions, and decrease AT1 receptor expression." (PMID 40134933, 2025). "In overweight patients, MAO contributes to cardiac oxidative stress in basal conditions and those that mimicked the renin–angiotensin system activation and hyperglycemia and can be targeted with empagliflozin and dapagliflozin, as novel off-target class effect of the SGLT2i." (PMID 39042348, 2025). "This may be attributed to the fact that the renin–angiotensin system in diabetic patients is activated by chronic hyperglycaemia." (PMID 39392052, 2024). "In addition, hyperglycemia, altered lipid metabolism, low-grade inflammation, over-activation of the renin-angiotensin-aldosterone system (RAAS), and overhydration (OH) increase diabetic CKD progression." (PMID 36874334, 2023). "Several components of the diabetic environment, such as hyperglycemia, the renin-angiotensin system and oxidative stress, can activate the inflammatory process in the kidney, which in turn can release harmful molecules, such as pro-inflammatory cytokines and reactive oxygen species." (PMID 35955405, 2022). "Furthermore, the current therapeutic options, including blood pressure optimization, optimal control of hyperglycemia and lipid levels, and maximizing the renin-angiotensin-aldosterone system blockade can only slow but not block the progression of DKD." (PMID 36035169, 2022). "The renin-angiotensin-aldosterone-system is activated by hyperglycemia in diabetic patients." (PMID 35843953, 2022). "The combination scheme has proven to be efficient in inhibiting the renin-angiotensin system that is mediated by hyperglycemia and in releasing smaller amounts of TGF-β1, which is ultimately involved the development of interstitial fibrosis and mesangial and tubular hypertrophy." (PMID 36699147, 2021). "Taken together, these data suggest that oxidative stress, but not hyperglycemia or the renin-angiotensin system, is the principal factor underlying the upregulation of clusterin expression in podocytes under diabetic conditions." (PMID 32913257, 2020). "The present study determined that tanshinone IIA could decrease the production of ANG II by inhibiting renin activity, consequently protecting mice with hyperglycaemia from bone deteriorations." (PMID 32202179, 2020). "Furthermore, elevated glucose levels stimulate RAAS, so hyperglycemia, through enhanced renin activity, stimulates local angiotensin (Ang)II synthesis." (PMID 32640692, 2020). "Meanwhile, hyperglycemia activates the renin-angiotensin-aldosterone system (RAAS)." (PMID 33134388, 2020). "Hyperglycemia and hyperinsulinemia are usually accompanied by increased free fatty acid levels, systemic and tissue inflammation, oxidative stress, and activation of the renin–angiotensin–aldosterone system and the sympathetic nervous system." (PMID 31684945, 2019). "One could be hypothesized that CMD and albuminuria share common hyperglycemia-induced pathways including low-grade pro-inflammatory state, chronic ischemia, oxidative stress and activation of the renin-angiotensin-system." (PMID 29325551, 2018). "From these results we consider that increased int-renin by hyperglycemia may afford the cell protection from H/R." (PMID 29295576, 2017).
Hyperglycemia (continued). "This might be caused by the anti-hyperinsulinemic and anti-hyperglycemic effects of asiatic acid, since there are substantial data to confirm that chronic hyperinsulinemia and hyperglycemia can enhance renin-angiotensin system." (PMID 27121076, 2016). "The correlation between hyperglycemia and oxidative stress demonstrated in clinical and experimental studies may be due to the upregulation of local renin-angiotensin systems (RAS)." (PMID 21829510, 2011). "Physiologically, it is plausible that hyponatremia could be secondary to increased renal sodium wasting from severe osmotic diuresis, transcellular water shifting from hyperosmolality and hyperglycemia, and increased renin–aldosterone–angiotensin system activation." (PMID 40880442, 2025). "The long-term chronic hyperglycemia may lead to oxidative stress response, inflammatory response, enhanced renin-angiotensin-aldosterone system (RAAS) activity, and vascular endothelial cell dysfunction, in which common pathogenesis could also be observed in the occurrence and development of DR." (PMID 37323224, 2023). "Persistent hyperglycemia can induce diastolic dysfunction through various mechanisms, including abnormal glucose and lipid metabolism, inflammation, oxidative stress, activation of the renin-angiotensin-aldosterone system (RAAS), and myocardial microvasculopathy." (PMID 38174338, 2023). "These compounds have been shown to prevent the increase in MCP-1, IL-6, renin, and fibronectin mRNA expression and the secretion of MCP-1 to the culture media induced by hyperglycemia in cultured podocytes." (PMID 40134933, 2025). "The activation of these processes is the consequence of the stimulation of increased renin–angiotensin–aldosterone (RAAS) activity, increased AGEs, insulin resistance and hyperglycemia." (PMID 39125850, 2024). "In the present study, we report that SD rats with STZ-induced hyperglycemia for 7 days exhibit augmentation of PRR, and prorenin and renin proteins expression in the CD of the kidney." (PMID 34226610, 2021). "According to a previous study, hyperglycemia is responsible for NF-κB overexpression, regulating NADPH-dependent oxidative stress and the renin-angiotensin system, which are involved in the development of DN." (PMID 32425787, 2020). "Additionally, IR-induced hyperglycemia upregulates the expression of angiotensinogen, angiotensin-converting enzyme (ACE), and angiotensin II, leading to overactivation of the renin–angiotensin–aldosterone system (RAAS)." (PMID 40964523, 2025). "By reducing the inflammatory and fibrotic markers brought on by hyperglycemia, combining SGLT-2 inhibitors with renin-angiotensin-aldosterone system (RAAS) blockers provide a unique strategy to slow the progression of DKD that is more successful than using either medication alone." (PMID 36733548, 2023). "Combining sodium-glucose cotransporter-2 inhibitors and renin-angiotensin-aldosterone system blockers is a novel way to slow down the course of DKD by lowering inflammatory and fibrotic indicators brought on by hyperglycemia, which is more effective than using either medicine alone." (PMID 36733548, 2023). "Treatment with 2,3,5,4′-tetrahydroxystilbene-2-O-β-d-glucoside could inhibit hyperglycaemia-induced mRNA and protein expression of AGT, renin, ACE, and AT1R in mice with DN induced by streptozotocin." (PMID 36059935, 2022). "As demonstrated by the DHE staining and FOX assay, both superoxide anion and H2O2 generation were significantly increased in conditions that mimicked the activation of the renin–angiotensin–aldosterone system (RAAS), acute inflammation, and uncontrolled hyperglycemia, respectively." (PMID 36556423, 2022).
Hyperglycemia (continued). "Hyperglycemia thoroughly instigates several cascades contributing to retinal vascular endothelial dysfunction, such as oxidative stress, inflammatory processes, protein kinase C (PKC) activation and renin-angiotensin system (RAS)." (PMID 33481907, 2021). "Moreover, decreased Na:K is suggestive of increased aldosterone activity and supports fact that persistent hyperglycemia stimulates the ANG and renin expression in tubular and mesangial cells." (PMID 33170841, 2020). "On the other hand, hyperglycemia has potent but reversible oxidizing effects on LDL-particles, resulting in increased oxidative stress which may activate renin-angiotensin system via cross-talks, leading to increased blood pressure." (PMID 25121493, 2014). "Persistent hyperglycemia in DKD patients triggers inflammatory pathways, including nuclear factor-κ B (NF-κ B), via mechanisms involving oxidative stress, the buildup of advanced glycation end products (AGEs), and activation of the renin-angiotensin system (RAS)." (PMID 40519516, 2025). "In diabetic conditions, hyperglycemia is responsible for suppressing the endothelial NO synthase (NOS), contributing to excessive ROS formation; however, it also enhances the overproduction of vasoconstrictor substances, such as endothelin 1 and the activation of the renin-angiotensin system." (PMID 36699147, 2021). "Notably, moderate hyperglycemia without glycosuria can enhance plasma renin activity and mean glomerular pressure, resulting in hyperfiltration and glomerulosclerosis." (PMID 36699147, 2021). "ACE-I treated group was really specific to the inhibition of the renin-angiotensin-aldosterone system rather than secondary to i) lower body weight, thus less hyperfiltration and less glomerular hypertrophy, ii) less hyperglycemia and most importantly iii) lower blood pressure." (PMID 25142208, 2014). "Interestingly, C66 administration does not affect angiotensinogen and renin expression, but significantly reduced ACE mRNA levels (P < 0.001), indicating that the reduction in Ang II level by C66 may result from its inhibition of hyperglycaemia-induced ACE overexpression." (PMID 24330074, 2014).